CD7 (CD7 molecule)
Diseases named in the same sentence as CD7 in open-access papers (continued):
Sharing a sentence is not in itself a finding about the gene and the disease.
tumor (continued). "PMBC-derived cells had malignant clones expectedly exhibiting a dominant clonotype (TRBV7-2 and TRAAV2), copy number variations, decreased expression of CD7, and aberrantly elevated expression of KIR3DL2 (CD158k) and CD70, which are known to be tumor-associated." (PMID 40941016, 2025). "Although K12 CAR-T cells had similar cytotoxicity toward CD7-positive tumor cell lines as scFvCD7 CAR-T cells in short-term cytotoxicity assays, K12 CAR-T cells were more prominently activated and secreted more IFN-γ and had a prolonged persistence in vitro compared to scFvCD7 CAR-T cells." (PMID 40589566, 2025). "Thus, K12 CAR-T cells had prominent CD7-restricted cytotoxic activity, also in a sequential killing assay in which cytotoxicity persisted toward CD7-positive tumor cell lines (CEM, Molt-4) for at least six rounds." (PMID 40589566, 2025). "The GARP expression on the cell surface was positively correlated with the tumor population size (CD4+/CADM1+/CD7−; “N” fraction) and soluble IL-2R, suggesting that ATL cases with high GARP+ ATL cells may be clinically more aggressive." (PMID 40759773, 2025). "Notably, when comparing K12 CAR-T cell cytotoxicity toward CD7-positive tumor cells, it was found to be comparable to that of scFvCD7 CAR T cells in a first cytotoxicity assay." (PMID 40589566, 2025). "Although our data showed that J87-Dxd could efficiently and specifically kill CD7-expressing tumor cells in vitro and in vivo, there were still limitations of our study." (PMID 38254706, 2024). "used a transgenic model of AML and CD7 CAR‐T cells to target CD7+ tumour cells." (PMID 38712978, 2024). "FHVH-derived CD5/CD7 bispecific CAR-T cells with CD5 and CD7 deletion had showed potent antitumor activity against T cell malignancies and tandem CARs could be conducive to mitigating tumor antigen escape." (PMID 39462383, 2024). "One of them (E012) also performed CD7 sequencing on pretreatment tumor samples, but no mutation was found." (PMID 37020231, 2023). "Tumor growth was assessed by measuring the percentages of CD5+/CD7+ PDX cells in total PBMC." (PMID 36978873, 2023). "Notably, when we focused the analysis on receptor-positive patients, the frequency of total CD7+CD56+ NK cells exhibiting the tumor markers MUC1 and HER2 appeared to be increased." (PMID 37593736, 2023). "After using CRISPR/Cas9 to knock out the genes that modulate CD5 and CD7 expression, the researchers compared the expression status and tumor-killing efficiency of tandem CARs and dual CARs (cell lines: Jurkat, CCRF-CEM, MOLT-4, SUP-T1, Raji; animal model: 6-week-old female NSG mice)." (PMID 37215124, 2023). "CD5/CD7 bispecific CAR-T cells are protective in the heterogeneous xenograft tumor model." (PMID 35332132, 2022). "The residual tumor contains 94.7% (430 cells) of C1 TAMs, which express CD7, CD3D and CD3E." (PMID 35784460, 2022). "In these common variants of T-CUS, loss of CD5 and/or CD7 is frequently encountered and should not by itself raise concern for neoplasia." (PMID 33673033, 2021). "Tumor cells in MF are classically CD3+CD4+CD8−, with frequent loss of CD7." (PMID 34118946, 2021). "Moreover, reduction of tumor burden indicated that CD7-CAR T cell prevents systemic leukemia progression." (PMID 34412685, 2021). "Once exposed to near-infrared light in tumor tissues, the anti-CD7-9R complexes within the fusion biomimetic carriers are released in response to structural decomposition and uptake by T cells due to receptor-mediated endocytosis based on CD7 and cell piercing peptide 9R." (PMID 34930285, 2021). "We found that treatment with control or CD7-KO NK cells led to equivalent tumor cell killing." (PMID 34423790, 2021). "Additionally, similar results were also obtained in preclinical assessments as bivalent CD7-redirected CAR-NKs considerably suppressed tumor outgrowth in xenograft models of T-ALL." (PMID 34620233, 2021).
tumor (continued). "The tumor cells characteristically show co-expression of one or more natural killer (NK)-cell-associated antigens (CD16, CD56, or CD57) and decreased CD2, CD5, or CD7 expression." (PMID 33673033, 2021). "Also, we measured total WNT5A mRNA levels by qPCR in the tumor cell fraction (CD4 + /CD7 − /CADM1 +) of an HTLV-1 carrier, a smoldering-type ATL patient, and 3 acute-type ATL patients, which were concentrated by the HAS-Flow method." (PMID 33603066, 2021). "Interestingly CD7+/CD34+ cells of the slow developing T-ALL4 contained a genetic subclone recurrently selected in xenografts that harbours a deletion of the tumour suppressor IKAROS." (PMID 27191650, 2016). "Interpretation of our findings on CD7 and CD56 implies that the low number of CD56 cells can cause up-regulation of progenitor T lymphocytes to enforce an immunological response against the tumor cells." (PMID 20604962, 2010). "In addition, anti-CD7 mAbs alone showed weak inhibition of tumor growth." (PMID 38254706, 2024). "Frameshift or missense mutations were detected in the four CD7-negative relapse patients in our study, suggesting that mutation may be a main cause of CD7 loss in tumor cells." (PMID 37020231, 2023). "Donor-derived CD7 CAR T cells may be particularly useful, when autologous CD7 CAR T-cell therapy is unavailable due to low quantity or quality of patient’s T cells, or risk of tumor contamination." (PMID 37020231, 2023). "However, the anti-tumor activity of anti-CD7-dgA is limited." (PMID 37215124, 2023). "Thus, we suspect that tumor cells could send a certain signal to turn off or down-regulate CD7 expression in the TIC T cells so that it could reduce the migration of the T cells into the tumors." (PMID 29112124, 2017). "Tumor cells expressed T-cell markers (CD2, CD3, CD5, CD7; heterogeneous) and cytotoxic markers (TIA-1) and showed CD30 and CD56 positivity, with EBV positivity confirmed by EBER in situ hybridization." (PMID 41744967, 2026). "NK cells (CD7+CD56+CD3−) and MAIT cells (CD3+CD161+IL18-R+) were identified as separate immune clusters and were significantly enriched in the tumour stroma compared with the parenchyma." (PMID 39349005, 2025). "These include targets expressed in hematological malignancies (such as BCMA, CD19, CD20, CD13, CD38, CD33, CD72, and CD7), solid tumors (such as PSMA, FGFR4, and GPC2) and tumor microenvironment (such as VEGFR2, EIIIB, PD-L1, and CD105)." (PMID 40474230, 2025). "We performed cell abundance analysis across CMS groups and found that CD8+ T subsets, Lin− CD7+ cells and DNT cells were enriched in CMS1 tumours, and that CD8+ T subsets and myeloid cell subsets were increased in CMS3 tumours." (PMID 39934971, 2025). "Tumor cells in MEITL are typically CD3+, CD5−, CD7+, CD4−, TIA-1+, granzyme B+, perforin+, and CD103+." (PMID 39447336, 2024). "Immunohistochemical staining of the tumor cells was positive for CD3, CD5, CD7, CD8, granzyme B, and TIA." (PMID 38404589, 2024). "The tumor cells also express cytotoxic molecules, including TIA-1 and granzyme B, whereas CD3 and CD7 are always diminished or lost." (PMID 38792976, 2024). "At present, several tumor antigens, such as CD33, CD123, CD7, C-type lectin-like molecule 1, CD38, TIM3, CD70, FLT3, and CD47, have been explored as target antigens for AML therapy." (PMID 39469704, 2024). "To minimize bias, we employed a combined approach, considering morphology from H&E slides and the distribution of tumor cells from additional immunohistochemistry staining such as CD3, CD4, CD8, CD7 and CD30." (PMID 37873805, 2023). "Base editor-edited universal CD7 CAR T-cells can replace existing CD7 CAR T-cells and hold promise for patients with insufficient healthy T cells or rapid tumor progression." (PMID 37215124, 2023).
tumor (continued). "They constructed monovalent CD7-CAR-NK-92MI and bivalent dCD7-CAR-NK-92MI cells using the CD7 nanobody VHH6 sequence and found that they exhibited high efficiency and specific anti-tumor activity on T-cell leukemia cell lines and primary tumor cells." (PMID 37215124, 2023). "An inguinal LN biopsy appeared as a tumor-cell-rich AITL, with abundant lymphoma cells, clear cytoplasm, and arborizing vessels, and expressed a TFH immunophenotype (CD3+, CD5+, CD7-, CD4+, strong ICOS, and PD1), though CD25 and FOXP3 were also positive." (PMID 37500795, 2023). "So far, clinical trials have utilized both autologous and allogeneic anti-CD7 CAR-T cells and have shown great promise regarding survival, tumor regression, and PFS." (PMID 38090582, 2023). "have recently developed a “2-in-1 strategy” of knocking out the CD7 locus and inserting an EF1α-driven CD7-CAR in this locus to achieve improved tumor rejection in a mouse xenograft model." (PMID 38090582, 2023). "Pathological characteristics of organoids including H&E staining and expression of protein markers (CK20, CDX-2, STAB2, CD7, PAX8) were consistent to those of the original tumor." (PMID 35721089, 2022). "Lymphocytes in the intra-epithelial compartment are described as having a phenotype that is similar to or consistently discordant with that of the invasive tumor and they must also express some pan-T-cell markers such as CD2, CD3, CD5, CD7." (PMID 36451465, 2022). "The fratricide-resistant FHVH-derived CD5/CD7 bispecific CAR-T cells have potent antitumor activity against T-cell malignancies, and tandem CARs are more effective than dual CAR in preventing tumor escape in heterogeneous leukemic cells." (PMID 35332132, 2022). "Degranulation was a prerequisite for perforin-granzyme-mediated tumor-killing of CAR-T cells, CD5/CD7 bispecific CAR-T cells upregulated CD107a expression after co-incubated with Jurkat, CCRF-CEM, MOLT-4, SUP-T1, CCRF-CD5KO cells, and CCRF-CD7KO cells." (PMID 35332132, 2022). "Normal CD4+ T lymphocytes corresponding to AITL tumor cells and the normal CD4+CD7- T-cell population in BM, PB and tissues were polyclonal." (PMID 36160159, 2022). "This case demonstrated that CD7-CART was a potent and safe salvage therapy in relapsed/refractory ETP-ALL/LBL patient with high tumor burden.Trial registration: ClinicalTrials." (PMID 35130959, 2022). "T-cell malignancies represent the other extreme, where all/most T-cells express the target, as does the tumor (i.e. CD3, and CD7) and therefore target deletion is essential." (PMID 35422095, 2022). "When compared to CD7-negative CD7-CAR-T cells, NS7CAR-T cells exhibited similar anti-tumor properties and have already passed phase 1 clinical trial recruiting patients with T-ALL or T-cell lymphoblastic lymphoma (NCT04572308)." (PMID 36248810, 2022). "Similar to EATL, tumor cells in MEITL are typically CD3+, CD5−, CD7+, CD4−, TIA-1+, granzyme B+, perforin+, and CD103+." (PMID 34830926, 2021). "Tumor cells typically exhibit a CD2+/−, cytoplasmic CD3+, CD4−, CD7+, CD8−, CD56+, CD103−, and TIA1+ phenotype." (PMID 34830926, 2021). "Tumor cells in all 20 cases were strongly positive for CD3 and CD7, while CD2(19/20), CD43(19/20), CD8(17/20), and CD56(15/20) were positive for partial tumor cells." (PMID 34895266, 2021). "We devised a simplified staining panel (DAPI, CD3, CD4, CD7, CD8, CD25, FoxP3, and PD-1) that captured the PD-1+ CD4+ T cells, tumor cells, and Tregs used to calculate the SpatialScore." (PMID 34795254, 2021). "First, second and third generation CAR NK cells have been generated, using lentiviral vectors, to target tumor antigens such as CD19, CD20, CD33, CD7, CD22, ErbB2 and EGFR." (PMID 33450862, 2021). "CAR-NK cells have been tested for tumor antigens (CD19, HER2, CD33, CD7, MUCI, and NR) and SARS-CoV-2 infected cells." (PMID 32731404, 2020).
tumor (continued). "Tumor cells were commonly positive for TDT (21/26, 80.8%), CD3 (29/31, 93.5%), and CD7 (25/27, 92.6%), and they were variably positive for CD5 (16/24, 66.7%), CD99 (14/19, 73.7%), CD2 (12/18, 66.7%), and CD1a (13/21, 61.9%)." (PMID 28566711, 2017). "Based on immunohistochemical staining, the phenotype of the tumor cells was CD3+, CD43+, CD56+, TIA-1+, CD30+, CD4-, CD5-, CD7-, CD8-, CD20- and CD79a-." (PMID 26126576, 2015). "CD7 and CD2 are expressed in varying degrees, and in approximately half of all cases, tumor cells are CD68+ and exhibit a specific cytoplasmic granular shape (i.e., multifocal color imaging of the Golgi apparatus)." (PMID 25663917, 2015). "Forexample, in patient 27, whose bone marrow had only one clonalDβ–Jβ rearrangement, the surface of the tumor cells did nothave CD3, CD5, CD4, or CD8, but only CD2 and CD7." (PMID 26483968, 2015). "Immunohistochemically, the tumor cells were cytokeratin -, vimentin +, CD3+, CD45RO+, CD5-, CD7-, CD4-, CD8-, CD10-, CD20-, CD30-, CD79a-, CD138-, CD56-, granzyme B-, TIA-1 cytotoxic granule-associated RNA binding protein (TIA-1) + and ALK-." (PMID 22931631, 2012). "Immunohistochemically, tumor cells showed CD3+, CD45RO+, CD5-, CD7-, CD4-, CD8-, CD10-, CD20-, CD30-, CD79a-, CD138-, CD56-, granzyme B-, TIA-1+ and ALK-." (PMID 22931631, 2012). "The tumor cells are positive for one or more pan-T-cell antigens (CD2, CD3, CD5, or CD7) and CD20 with monoclonal rearrangements of TCR γ or β without rearrangement of the IgH gene." (PMID 23031227, 2012). "PTCL is diagnosed when tumor cells express the mature T cell antigens CD2, CD3, CD4, CD5, CD6, or CD7 on immunohistochemical staining." (PMID 21310044, 2011). "In addition, immunohistochemical analysis revealed that tumor cells were positive for CD3, CD43, CD56, TIA1, granzyme B, CD2, CD4, and CD7." (PMID 40433378, 2025). "However, this study supports the importance of thorough tumor characterization and the potential use of CD7-RTX CAR T cells to treat a variety of malignancies expressing CD7." (PMID 40821791, 2025). "However, when the CD7-RTX CAR T cells bind the target, an MHC-independent intracellular cascade occurs resulting in cytotoxic killing of the tumor cell." (PMID 40821791, 2025). "Immunohistochemistry of MEITL tumor cells usually detects CD3, CD7, CD8, CD43, and CD56 expression." (PMID 38520011, 2024). "In addition, CD7 CARCD7-T-cells demonstrated in vivo persistence and protection of NGS mice receiving 1×104 CCRF (T-ALL) or 3×106 BV173 (B-ALL) cells from tumor relapse." (PMID 37215124, 2023). "Although there were not significant differences between receptor-negative BC patients and HDs, some of the tumor markers analyzed were found upregulated on CD7+CD56+ NK cells from receptor-positive BC patients when compared with HD." (PMID 37593736, 2023). "Gal-1 is known also by inducing apoptosis on T-cells, but the lack of CD7 expression and different CD7 glycosylation in tumor cells on skin lesions and Sézary T-cell lines seems to confer Gal-1 induced apoptosis resistance to the tumor cells." (PMID 35055124, 2022). "We observed various responses to palbociclib concerning both models (CD3, CD7) harboring a loss of CDKN2A/2B, and no tumor efficacy in the non-CDKN2A/2B-deleted PBRM1-mutated PDX (CD39)." (PMID 36505864, 2022). "Flow cytometric detection of human blasts (CD45+/CD19+ for B-ALL and CD45+/CD5+ or CD45+/CD7+ for T-ALL, based on surface marker phenotyping in the original tumor material) showed engraftment in all but one (patient #0031) patient sample, resulting in an engraftment rate of 94.4%." (PMID 35011712, 2022). "In our in vivo pharmacological program, the CD3 model harboring CDKN2A/2B showed a significant tumor growth inhibition (p = 0.02), while the CD7 model showed no tumor response (p = 0.85)." (PMID 36505864, 2022).
tumor (continued). "We designed naturally selected CD7 CAR-T cells to analyse various functions and in vitro antileukaemic efficacy based on flow cytometry, and xenograft models were used to validate in vivo tumour dynamics." (PMID 36517851, 2022). "For the CD7 xenograft, we did not observe any tumor growth response to both palbociclib and volasertib (p = 0.85 and p > 0.99, respectively), as well as for the CD39 xenograft without CDKN2A/2B deletion (p = 0.40 and 0.058, respectively)." (PMID 36505864, 2022). "It was found that, in AITL, patients expressing CD7 had a better prognosis, whereas patients expressing CD38 and Ki-67 had a poorer prognosis, It may suggest that tumor cells with more active proliferative capacity are more aggressive." (PMID 36466894, 2022). "Due to the unselective elimination of normal T cells and malignant cells, pan-T cell antigen-targeting CAR-T cells, such as CD5, CD7, and CD3 T cells, will most likely be useful as a temporary tumor burden-control strategy instead of a permanent treatment option." (PMID 35882880, 2022). "Tumor control was comparable in mice with control or CD7-KO HSCs as compared with a cohort of mice without prior HSC engraftment." (PMID 34423790, 2021). "CD7– T cells could be manufactured into CD19- and CD33-targeting CAR T cells that were able to kill tumor cells expressing the target antigen." (PMID 34423790, 2021). "Notably, the tumor cell phenotype identified by CODEX in this cohort (i.e., decreased expression of CD7 and increased expression of CD25 and Ki-67), was critical for establishing this condensed staining panel and was readily transferred to the Vectra platform." (PMID 34795254, 2021). "Given that CAR T cells disrupted for CD7 retain potent functional activity, it appears that CD7 signalling, and by proxy SECTM1 activity, may be redundant for anti-tumour function." (PMID 34035409, 2021). "Flow cytometry analyses showed CD7 and CD20 positivity in tumor cells." (PMID 32328320, 2020). "Abrogating CD7 expression by either mechanism did not affect proliferation or short-term effector function of T cells and preserved their anti-tumor activity." (PMID 30891427, 2019). "The mAb conjugate produced no severe CD7-directed toxicities, but tumor responses were modest, likely due to limited activity of murine antibodies in human patients." (PMID 30891427, 2019). "To investigate whether NK cells could mediate tumor elimination by anti-CD47 antibody in vitro, we utilized human NK cells (CD3−CD56+CD7+) as effectors." (PMID 28484448, 2017). "The immunophenotype of tumor cells is CD3+, CD7−, CD4+/CD8−, and CD25+." (PMID 25587470, 2014). "Furthermore, the tumor cells stained positive for CD2, CD3, CD7, CD99, Perforin and, remarkably, CD8." (PMID 22497840, 2012). "The patient's neoplasm was CD7+ and no malignant skin lesions were identified thus the probability of it representing a metastatic cutaneous gamma/delta T-cell lymphoma is unlikely." (PMID 17963509, 2007). "In anti-tumor applications, research has predominantly focused on well-validated targets such as CD19, CD20, and BCMA while in vivo CAR-T generation primarily employs lentiviral-based CAR gene delivery, with targeting strategies involving CD3, CD8, CD7, and anti-TCR nanobody." (PMID 41250215, 2025). "Flow cytometric analysis of the bone marrow and lymph nodes indicated that the tumor cells of both were of the same origin and mainly expressed stem cell markers and CD7, no myeloid-specific markers, T-lymphoblastic-related markers, and B-lymphoblastic-related markers." (PMID 38277531, 2024). "The CD7 UCAR-T cells could induce the killing of primary T-ALL cells in vitro, with high degranulation level and proinflammatory cytokines release, and were able to reduce tumor growth and increase mice survival in vivo." (PMID 36624522, 2023).